TMEM108 (transmembrane protein 108)
Description:
Transmembrane protein required for proper cognitive functions. Involved in the development of dentate gyrus (DG) neuron circuitry, is necessary for AMPA receptors surface expression and proper excitatory postsynaptic currents of DG granule neurons. Regulates the organization and stability of the microtubule network of sensory neurons to allow axonal transport. Through the interaction with DST, mediates the docking of the dynein/dynactin motor complex to vesicle cargos for retrograde axonal transport. In hippocampal neurons, required for BDNF-dependent dendrite outgrowth. Cooperates with SH3GL2 and recruits the WAVE1 complex to facilitate actin-dependent BDNF:NTRK2 early endocytic trafficking and mediate signaling from early endosomes.
Synonyms: RTLN; MGC3040; CT124
Tractability: Antibody: UniProt places it where antibodies can reach, with medium confidence; UniProt predicts a signal peptide or a membrane-spanning region; the Human Protein Atlas places it where antibodies can reach.
Gene: Protein-coding gene on chromosome 3 (133,038,322 to 133,397,775, forward strand). Ensembl gene ENSG00000144868.
Subcellular location: Membrane; Postsynaptic density; Endosome membrane; Cell projection, axon; Cell projection, dendrite; Early endosome
Subcellular location (Human Protein Atlas): Cytosol; Plasma membrane; Nucleoli; Vesicles
Gene Ontology:
Molecular function: protein binding
Biological process: cellular response to brain-derived neurotrophic factor stimulus; dendrite extension; dentate gyrus development; modulation of excitatory postsynaptic potential; neuron projection development; positive regulation of neurotrophin TRK receptor signaling pathway; postsynaptic density organization; receptor-mediated endocytosis; retrograde axonal transport; regulation of neurotransmitter receptor localization to postsynaptic specialization membrane
Cellular component: axon; early endosome; endosome membrane; membrane; postsynaptic density; somatodendritic compartment; axon cytoplasm; dendrite; glutamatergic synapse; postsynaptic density membrane
Genetic constraint (gnomAD): Loss-of-function variants: 12 observed, 33.19 expected, observed/expected ratio (o/e) 0.36, 90% interval 0.23 to 0.59. The upper end of that interval is the gene's LOEUF score, 0.59, which puts it in group 2 of 6, group 1 being the genes least tolerant of losing a copy. Missense variants: 671 observed, 773.34 expected, observed/expected ratio (o/e) 0.87, 90% interval 0.81 to 0.93. Synonymous variants: 284 observed, 316.81 expected, observed/expected ratio (o/e) 0.9, 90% interval 0.81 to 0.99.
Homologues: Orthologues: chimpanzee TMEM108 (99% identical), macaque TMEM108 (95% identical), pig TMEM108 (80% identical), dog TMEM108 (77% identical), mouse Tmem108 (77% identical), rat Tmem108 (75% identical), guinea pig TMEM108 (75% identical), rabbit TMEM108 (64% identical), zebrafish tmem108 (27% identical).
Diseases named in the same sentence as TMEM108 in open-access papers:
TMEM108 is named in the same sentence as 17 diseases in open-access papers, as found by Europe PMC text mining. Sharing a sentence is not in itself a finding about the gene and the disease. The quoted sentences say what the papers report.
schizophrenia (5 papers, 2018 to 2022). A major psychotic disorder characterized by abnormalities in the perception or expression of reality. "A Genome-wide association study (GWAS) found that TMEM108 is a susceptibility gene of psychiatric disorders, including schizophrenia, bipolar disorder, and major depression disorder." (PMID 35311004, 2022). "Genome-wide association study (GWAS) found that TMEM108 is a susceptibility gene of psychiatric disorder, including schizophrenia, bipolar disorder (BPD) and MDD." (PMID 30651970, 2019). "One of the top genes was Tmem108, which has been previously linked with schizophrenia and alcoholism (p-values < 10−5 for comparing these cells with OPCs and oligodendrocytes)." (PMID 31336988, 2019). "Transmembrane protein 108 (Tmem108) is a risk gene of psychiatric diseases including schizophrenia, bipolar disorder and major depression disorder." (PMID 30651970, 2019).
bipolar disorder (4 papers, 2019 to 2022). A disorder of the brain that causes unusual shifts in mood, energy, activity levels and the ability to carry out day-to-day tasks. "Transmembrane protein 108 (Tmem108), as a susceptible gene of bipolar disorder, is expressed higher in OL lineage cells than any other lineage cells in the central nervous system." (PMID 35410424, 2022). "Tmem108 is not only a susceptible gene of SCZ but also a risk gene of other psychotic disorders, such as bipolar disorder and major depressive disorder, which suggest Tmem108 have a complicated role in the psychotic pathology." (PMID 34690937, 2021). "Tmem108 inhibited OL progenitor cell proliferation and mitigated OL maturation in the corpus callosum, which may also provide a new role of Tmem108 involving bipolar disorder pathogenesis." (PMID 35410424, 2022). "Moreover, Tmem108 mutant mice exhibit mania-like behaviors, belonging to one of the signs of bipolar disorder." (PMID 35410424, 2022).
major depression disorder (4 papers, 2019 to 2022). "Because adult neurogenesis decreases in Tmem108 mutant mice, Tmem108 mutant mice may be linked to depression." (PMID 30651970, 2019). "Although Tmem108 mutant impairs adult neurogenesis of the mice, it does not induce depression-like behavior but stirs manic-like behavior, suggesting Tmem108 is higher correlating with BD than depression." (PMID 35410424, 2022). "And furthermore, Tmem108 mutant mice behaviors in depression-like tests indicate that Tmem108 plays a complexity role in psychiatric disorders." (PMID 30651970, 2019). "In this study, the results showed that Tmem108 played a complexity role in psychiatric disorders, Tmem108 mutant mice had lower immobility than wild type mice in depression-like behavior tests, and adult neurogenesis of the hippocampal DG in Tmem108 mutant mice decreased." (PMID 30651970, 2019).
Stroke (3 papers, 2022 to 2024). Sudden impairment of blood flow to a part of the brain due to occlusion or rupture of an artery to the brain. "In human, TMEM108 is a candidate gene associated with stroke by GWAS." (PMID 36575369, 2022). "Emerging studies like novel ethnic-specific genetic variants, such as SUMOylation pathway in Indians, SFXN4 and TMEM108 in Africans indicate the involvement of different pathways among different ethnicities in stroke." (PMID 39268810, 2024).
alcohol addiction (1 paper, 2022). "GWAS found that TMEM108 is not only related to substance addiction, smoking withdrawal, and alcohol addiction, but also is a susceptibility gene of SCZ and BD." (PMID 35410424, 2022).
epilepsy (1 paper, 2022). A brain disorder characterized by episodes of abnormally increased neuronal discharge resulting in transient episodes of sensory or motor neurological dysfunction, or psychic dysfunction. "Tmem108 mutant mice quickly reached seizure stage 5 compared with the control mice, indicating Tmem108 involved the occurrence of induced epilepsy." (PMID 35410424, 2022).
Glucose intolerance (1 paper, 2021). Glucose intolerance (GI) can be defined as dysglycemia that comprises both prediabetes and diabetes. "In this research, we found that Tmem108 mutant mice exhibited glucose intolerance, insulin resistance, and disturbed metabolic homeostasis." (PMID 34690937, 2021).
Hyperglycemia (1 paper, 2021). An increased concentration of glucose in the blood. "Hyperglycemia occurs more often in SCZ patients than controls, implying that these two diseases share common biological mechanisms, here we demonstrate that Tmem108 mutant may represent such a comorbid mechanism." (PMID 34690937, 2021).
psychiatric diseases (5 papers, 2019 to 2022). "Transmembrane protein 108 (Tmem108) is a susceptible gene associated with multiple psychiatric diseases, including SCZ." (PMID 34690937, 2021). "TMEM108 is involved in adult hippocampal neurogenesis and linked to diverse psychiatric disorders." (PMID 32954517, 2020). "In the process of characterizing function of Tmem108 in psychiatric disorders, we found that Tmem108 is developmentally regulated and is required for glutamatergic transmission in DG." (PMID 30651970, 2019). "Furthermore, abnormal behaviors in Tmem108 mutant mice indicated that Tmem108 plays a complexity role in psychiatric disorders." (PMID 30651970, 2019). "Therefore, Tmem108 may play a complexity role in psychiatric disorders." (PMID 30651970, 2019).
tumor (1 paper, 2017). "TMEM108 and C3orf47 were positively correlated with tumor grade and eight genes, including LAD1, TIF1, FGF11, carbonic anhydrase 12 (CA12), G protein subunit α15 (GNA15), junction plakoglobin (JUP), plakophilin 1 (PKP1) and PPARD, were negatively correlated with the tumor grade of ESCC patients." (PMID 28904855, 2017). "Transmembrane protein 108 (TMEM108), C3orf47 and coenzyme Q8A (CABC1) were the top three genes positively correlated with tumor grade, whereas ladinin 1 (LAD1), TIAF1 and FGF11 were the top three genes negatively correlated with the tumor grade of ESCC patients." (PMID 28904855, 2017).
TMEM108 also shares sentences with these, for which no sentence is quoted: depression (2 papers); alcoholism (1); Insulin resistance (1); Lewy body dementia (1); myopia (1); Obesity (1); psychotic disorder (1).